BRD4 (bromodomain containing 4)
Diseases named in the same sentence as BRD4 in open-access papers (continued):
Sharing a sentence is not in itself a finding about the gene and the disease.
Kabuki syndrome (1 paper, 2025). Kabuki syndrome (KS) is a multiple congenital anomaly syndrome characterized by typical facial features, skeletal anomalies, mild to moderate intellectual disability and postnatal growth deficiency. "In Kabuki syndrome, mutations in histone lysine methyltransferase MLL4 and demethylase UTX reduce their ability to form phase-separated condensates, impairing recruitment of MED1/BRD4 and exclusion of PRC1/2." (PMID 40507965, 2025).
keratinization (1 paper, 2015). The process in which the cytoplasm of the outermost cells of the vertebrate epidermis is replaced by keratin. "In theory, overt keratinization is very important and sometimes pathognomonic for a scrutinized diagnosis of NMC; that is, it is assumed to be a relatively characteristic finding of NMC harboring a NUT gene rearrangement involving a gene other than BRD4." (PMID 25685583, 2015).
leiomyoma (1 paper, 2022). A well-circumscribed benign smooth muscle neoplasm characterized by the presence of spindle cells with cigar-shaped nuclei, interlacing fascicles, and a whorled pattern. "Tissue samples derived from 50 patients with EC and 14 patients with leiomyoma undergoing hysterectomy between January 2010 and June 2012 were used to validate and estimate the potential role of BRD4." (PMID 35902869, 2022).
lupus (1 paper, 2026). "BG mitigates lupus progression in mice, and its effects are linked to the modulation of macrophage phenotype and autophagic activity, a process associated with the miR-146a/BRD4 axis." (PMID 41766884, 2026).
mastocytosis (1 paper, 2025). A clonal myeloproliferative neoplasm characterized by the proliferation and accumulation of neoplastic mast cells in one or multiple organs or organ systems. "Although direct links between BRD4 mutations and mastocytosis are less established, its involvement in transcriptional regulation may influence mast cell behaviour and contribute to disease pathology indirectly." (PMID 41031827, 2025). "The results align with our previous findings, which determined TET2, DNMT3A, SETD2 and BRD4 genes as promising candidates for further analysis, warranting future study in a larger cohort of mastocytosis patients." (PMID 41031827, 2025).
memory impairment (1 paper, 2025). "A previous study reported that BRD4 inhibition affects essential synaptic proteins, leading to memory impairment and simultaneously reducing seizure susceptibility in mice." (PMID 40959274, 2025). "We then assessed whether pharmacological BRD4 inhibition improves ethanol-induced memory impairment using the open field test, novel object recognition (NOR), and Y-maze in ethanol-fed mice." (PMID 40959274, 2025).
metastatic cancer (1 paper, 2021). A carcinoma which has spread from the original site of growth to another anatomic site. "Interestingly, several well-known oncogenes linked to aggressive and metastatic cancer phenotype, including CXCL1, CXCL2, MYC, and BMP4, were included in this gene get, suggesting that BRD4 and STAT3 can coordinately regulate the oncogenic enhancer activity to promote tumor progression." (PMID 34290255, 2021).
myxoid liposarcoma (1 paper, 2022). A liposarcoma characterized by the presence of round non-lipogenic primitive mesenchymal cells and small signet ring lipoblasts within a myxoid stoma with a branching vascular pattern. "Likewise in myxoid liposarcoma, FUS‐DDIT3 and BRD4 were reported to co‐localize on enhancers and regulate expression of super‐enhancer‐associated genes." (PMID 35182012, 2022).
nasal polyp (1 paper, 2020). "The relationship between BRD4 and EMT was evaluated by the BRD inhibitor JQ1 and BRD4 siRNA in primary human nasal polyp–derived epithelial cells." (PMID 32923445, 2020).
nasopharyngeal carcinoma (1 paper, 2023). A carcinoma arising from the nasopharyngeal epithelium. "Treatment with the BRD4 inhibitor JQ1 significantly suppresses super-enhancer-associated ETV6 gene expression and induces nasopharyngeal carcinoma cell growth inhibition." (PMID 38135679, 2023). "In nasopharyngeal carcinoma cells, super-enhancers are enriched of BRD4, NF-κB, IRF1 and IRF2 transcription factors at the loci of critical oncogenes such as ETV6, high expression of which in human nasopharyngeal carcinoma tissues is correlated with poor patient prognosis." (PMID 38135679, 2023).
neurofibroma (1 paper, 2017). An intraneural or extraneural neoplasm arising from nerve tissues and neural sheaths. "To rule out that degradation of the total RNA isolated from the archival samples impairs accurate quantitation we also determined BRD4 mRNA levels in a set of fresh frozen plexiform neurofibromas (n = 7), atypical neurofibromas (n = 4) and MPNST (n = 11)." (PMID 28813519, 2017). "To further investigate whether BRD4 can serve as a target for treatment we determined the sensitivity of our cell line panel consisting of a neurofibroma and 5 MPNST cell lines, to the BET bromodomain inhibitor JQ1." (PMID 28813519, 2017). "The transcript levels of BRD4, EZH2 and TOP2A were determined in paired formalin-fixed paraffin-embedded (FFPE) neurofibroma/MPNST samples derived from the same NF1 patient and in a set of plexiform neurofibromas, atypical neurofibromas and MPNST." (PMID 28813519, 2017). "In this study we analyzed the expression level of three potential drug targets BRD4, EZH2, and TOP2A in selected human MPNST and neurofibroma samples from the Erasmus MC tissue bank." (PMID 28813519, 2017). "To confirm this putative key role of BRD4 in human MPNST pathogenesis, we evaluated the expression level of BRD4 in plexiform neurofibromas and MPNST samples." (PMID 28813519, 2017). "Both in the neurofibroma-MPNST pairs as well as in the fresh frozen samples we did not detect BRD4 overexpression in the MPNST samples." (PMID 28813519, 2017).
neuropathy (1 paper, 2022). A disorder affecting the nervous system that manifests with pain, tingling, numbness, and/or muscle weakness. "Moreover, in animals with neuropathy, both SUM52 and SUM35 were more effective in reducing pain symptoms than in naïve animals, highlighting how the role of HDAC and BRD4 is greater in the central nervous system after injury than after acute pain." (PMID 35501470, 2022).
oral cancer (1 paper, 2021). "When BRD4 expression is reduced, oral cancer cell growth and metastasis are inhibited." (PMID 34876902, 2021).
pancreatic NETs (1 paper, 2020). "In our study, we demonstrate that AtT20 cells express the BET family members Brd2, Brd3 and Brd4, with Brd2 being the most abundant, which is similar to data reported for MEN1-associated mouse pancreatic NETs and human pancreatic and bronchial NET cell lines." (PMID 31935194, 2020).
pancreatitis (1 paper, 2020). Inflammation of the pancreas. "Then, we examined the influence of BRD4 inhibition on pancreatitis severity during two experimental models of AP in vivo." (PMID 32457617, 2020). "Firstly, we tested JQ1, the inhibitor of BRD4 in caerulein hyperstimulation pancreatitis, a widely used and highly reproducible AP model." (PMID 32457617, 2020). "In summary, in this study, we showed that BRD4 expression is upregulated in various experimental models of pancreatitis." (PMID 32457617, 2020). "Therefore, we aim to explore the role of BRD4 using experimental models of pancreatitis." (PMID 32457617, 2020).
papillary carcinoma (1 paper, 2020). A malignant epithelial neoplasm characterized by a papillary growth pattern. "In the primary papillary carcinoma cells (“C1/C2”), treatment with ARV-825 (100 nM, 24h) similarly induced BRD4 protein degradation as well as downregulation of c-Myc, Bcl-xL and cyclin D1." (PMID 32163373, 2020).
plexiform neurofibroma (1 paper, 2017). An elongated and multinodular neurofibroma, formed when the tumor involves either multiple trunks of a plexus or multiple fascicles of a large nerve, such as the sciatic. "We examined BRD4 mRNA expression by qRT-PCR in a series of nine paired human MPNST and plexiform neurofibroma FFPE samples, each pair derived from the same patient." (PMID 28813519, 2017).
pneumoconiosis (1 paper, 2022). An occupational lung disorder caused by inhalation of dust particles. "Other treatments for IPF, such as the bromodomain containing 4 (BRD4) inhibitor JQ1, the type-2 histone deacetylase 2 (HDAC) inhibitor spiruchostatin A, and suberoylanilide hydroxamic acid, may also be useful for treatment of pneumoconiosis." (PMID 35096264, 2022).
progeria (1 paper, 2023). "Another interesting observation is that progeria patients do not typically develop cancer, possibly due to a potentially protective mechanism of bromodomain-containing protein 4 (BRD4)." (PMID 36980874, 2023).
prostate tumor (1 paper, 2025). "Rather than promoting EMT, BRD4 appears to enforce a collective migration phenotype in the prostate tumor setting—a cohesive strategy associated with high metastatic potential." (PMID 40407591, 2025).
retinopathy of prematurity (1 paper, 2017). A bilateral retinopathy characterized by neovascularization, scarring, retinal detachment, and eventually blindness. "In this regard, the ETS1–BRD4 interaction may represent a more selective therapeutic target than BRD4 itself, with potential applications to ameliorate diseases caused by excessive angiogenesis, such as retinopathy of prematurity." (PMID 28851877, 2017).
schistosomiasis (1 paper, 2025). An infectious disease caused by parasitic trematodes of the genus Schistosoma that colonize human blood vessels and release eggs that can cause granulomatous reactions leading to acute (swimmer's itch or acute schistosomiasis syndrome) or chronic disease. "The precise molecular mechanisms through which BRD4 modulates immune pathways in the context of schistosomiasis are still not fully understood." (PMID 40616163, 2025). "While this study provides a valuable foundation for understanding the role of BRD4 in schistosomiasis, several questions remain unanswered." (PMID 40616163, 2025). "BRD4 may serve as a valuable molecular target for understanding host–pathogen interactions and developing adjunct therapies against schistosomiasis." (PMID 40616163, 2025).
schwannoma (1 paper, 2020). A benign, usually encapsulated slow growing tumor composed of Schwann cells. "This may represent another mechanism through which cotargeting BRD4 and phosphorylation of ERK results in decreased protein level of BRD4 and impairment of schwannoma proliferation." (PMID 32960816, 2020). "As we expected, combined pharmacologic targeting of BRD4 and the MAPK pathway achieved promising therapeutic results on mouse schwannoma." (PMID 32960816, 2020). "Therefore, we tested the combined effect of a BRD4 inhibitor (JQ1) and MAPK pathway inhibitor (PD0325901, hereafter called 901) on schwannoma in vitro and in vivo." (PMID 32960816, 2020). "Interestingly, we also observed high BRD4 expression in YAP/TAZ-activated mouse schwannoma, indicating the therapeutic potential of BET inhibitors in the treatment of schwannoma." (PMID 32960816, 2020). "In addition, BRD4 inhibition by JQ1 partially blocked transcriptional activity of YAP/TAZ and reduced mouse schwannoma growth." (PMID 32960816, 2020).
seminoma (1 paper, 2025). A radiosensitive malignant germ cell tumor found in the testis (especially undescended), and extragonadal sites (anterior mediastinum and pineal gland). "Notable differences were observed through the assessment of primary and metastatic samples of seminoma, revealing BRD4 mutations were overrepresented in metastatic cases (p = 0.00125), while KIT mutations were more common in primary samples (p = 0.00191)." (PMID 41154418, 2025).
Simpson-Golabi-Behmel syndrome (1 paper, 2020). Simpson-Golabi-Behmel syndrome is a rare X-linked multiple congenital anomalies syndrome, characterized by pre- and postnatal overgrowth, distinctive craniofacial features, variable congenital malformations, organomegaly and an increased tumor risk. "Increasing reports have shown that the loss of BRD4 function recruits bio-active regulators, which facilitate adipocyte formation of 3T3-L1 cells and TNF-α-treated human Simpson-Golabi-Behmel syndrome adipocytes." (PMID 32575577, 2020).
skin inflammation (1 paper, 2022). "Collectively, these results suggest that deletion of Brd4 in Tregs (Ox40-Cre mediated) weakens their regulatory functions, which contributes to γδ T cell activation and skin inflammation." (PMID 36256455, 2022). "Immunofluorescence staining of the skin tissue further confirmed the increased production of IL-17 in the epidermis of Brd4fl/fl Ox40-Cre mice, suggesting that γδ+ T cells are likely the effector cells in skin inflammation in conditional Brd4-deleted mice." (PMID 36256455, 2022). "Thus, our data demonstrate an unexpected role of BRD4 in regulating skin follicle stem cells and skin inflammation." (PMID 36256455, 2022). "Thus, our results reveal a role for the chromatin reader BRD4 in regulating the HFSCs and skin inflammation." (PMID 36256455, 2022). "Thus, our data reveal potentially novel insights into the roles of BRD4 in the control of both immune cells and nonimmune cells in tissue-specific skin inflammation." (PMID 36256455, 2022). "Interestingly, deletion of Brd4 in Foxp3+ Tregs, which also constitutively express OX40, compromised their suppressive functions, and this, in turn, contributed to the enhanced activation of γδ T cells, as well as the severity of dermatitis and hair follicle destruction." (PMID 36256455, 2022). "Additionally, deletion of Brd4 in follicle stem cells also rendered them sensitive to cell death, which in turn triggered the activation of γδ T cells and production of potent inflammatory cytokines, including IL-17A, IL-17F, and IFN-γ, that subsequently mediate skin inflammation." (PMID 36256455, 2022).
skin squamous cell carcinoma (1 paper, 2020). A carcinoma arising from the squamous cells of the epidermis. "Bromodomain-containing protein 4 (BRD4) is a potential therapeutic target of skin squamous cell carcinoma (SCC)." (PMID 32371868, 2020).
tauopathy (1 paper, 2024). Neurodegenerative disorders involving deposition of abnormal tau protein isoforms (tau proteins) in neurons and glial cells in the brain. "Our work identifies Brd4 as a regulator of microglial synapse elimination in tauopathy, and more broadly provides tools and methodology to investigate PSP pathophysiology and therapeutics through an unbiased discovery-driven approach." (PMID 39294122, 2024). "Our findings implicate Brd4 as a regulator of microglial synaptic elimination in tauopathy and provide an unbiased approach for identifying mechanisms and therapeutic targets in PSP." (PMID 39294122, 2024).
Wilms tumor (1 paper, 2024). An embryonal neoplasm characterized by the presence of epithelial, mesenchymal, and blastema components. "In preclinical studies of Wilms tumor, the bivalent BRD4 inhibitor AZD5153 led to reduced MYC levels in cell lines derived from anaplastic and non-anaplastic Wilms tumor, and inhibited tumor growth in patient-derived xenografts." (PMID 39766049, 2024).
ZIKV infection (1 paper, 2018). "Since there are no annotated isoforms of this predicted mass, the data suggest that BRD4 is cleaved during ZIKV infection." (PMID 30511641, 2018). "Specifically, we observed that the FMRP targets, FXR2, TLN1, BRD4, and PNPLA6 were elevated at the protein level as a consequence of ZIKV infection." (PMID 30511641, 2018).
cancer (697 papers, 2006 to 2026). A tumor composed of atypical neoplastic, often pleomorphic cells that invade other tissues. "Despite playing critical roles in general transcription, inhibition of CDK7 and BRD4 have been implicated in preferential downregulation of cancer-related genes, such as MYC, thereby selectively killing cancer cells." (PMID 41505030, 2026). "Here, we identify a high level of genetic correlation between ASXL1 and the major transcriptional activator BRD4 in cancer cells and characterize the molecular mechanism underlying this correlation." (PMID 41702923, 2026). "It has been reported that cancer - associated fibroblasts (CAF) can induce the phosphorylation of BRD4 at tyrosine 97/98 in colorectal cancer via the interleukin − 6/8 - JAK2 transduction." (PMID 39838405, 2025). "This inverse association between TXNIP and BRD4 expression was further corroborated through an analysis of the TCGA pan-cancer database." (PMID 41249136, 2025). "Small-molecule BETi targeting of the epigenetic reader BRD–containing proteins BRD2, BRD3, and BRD4 has been developed to cause cancer cell death." (PMID 40632844, 2025). "BRD4 commonly associates with cancer-maintenance genes (e.g. MYC, RUNX1) that are decorated with high-level acetylation, which leads to selective cancer dependency on BRD413." (PMID 39651888, 2025). "Dysregulation of BRD4 has been implicated in various diseases including cancer, inflammatory disorders, and fibrosis, making it an important therapeutic target." (PMID 40507351, 2025). "BRD4 inhibitors can also cause cell cycle arrest and induce apoptosis in cancer cells, further inhibiting their proliferation." (PMID 38473320, 2024). "Abnormal expression of Brd4 has been implicated in the advancement of numerous cancer types, leading to the successful use of bromodomain‐targeting antagonists in tumour therapy." (PMID 39010274, 2024). "Given BRD4’s involvement in these fundamental processes, it is implicated in various diseases, including cancer and inflammation, making it a promising target for therapeutic development." (PMID 39066258, 2024). "Deregulation of BET proteins, particularly BRD4, has been implicated in the development of various diseases, especially cancer." (PMID 38473320, 2024). "Presently, among the SE-associated elements identified as targets for cancer therapy, notable candidates include BRD4, CDK7, CDK8, CDK19, and EP300." (PMID 38365636, 2024). "Its role is characterized primarily by the modulation of the expression of key cancer-related genes, particularly those encoding Myc and BRD4." (PMID 39335515, 2024). "Here we described the biophysical impact of chromatin binding on condensate formation by BET family protein BRD4, which is biologically implicated in potent transcriptional activation, and is commonly misregulated in cancer." (PMID 38656803, 2024). "Dysregulation of BRD4 has been linked to various cancers, where it contributes to cell proliferation and tumor progression." (PMID 38500181, 2024). "BRD4 is the main BET protein associated with cancer and serves as a transcriptional regulator that controls gene expression of key oncogenes such as MYC." (PMID 38893083, 2024). "This decision is underpinned by the observed anticancer effects associated with BRD4 inhibitors across multiple cancer types, demonstrating effectiveness both independently and in conjunction with conventional agents." (PMID 38473320, 2024). "A recent study further delineates a role in maintaining genomic integrity, whereby the loss of BRD4 in cancer cells induced DNA damage and cell death due to an accumulation of transcription-replication conflicts and failure of checkpoint signaling." (PMID 38874522, 2024). "BRD4 was found to be highly expressed in cancer tissues and is believed to be associated with poor prognosis in cancer patients." (PMID 38565708, 2024).